GLP1R (glucagon like peptide 1 receptor)
Diseases named in the same sentence as GLP1R in open-access papers (continued):
Sharing a sentence is not in itself a finding about the gene and the disease.
Hepatic steatosis (114 papers, 2012 to 2026). Steatosis is a term used to denote lipid accumulation within hepatocytes. "In this study, we investigated the possible mechanisms underlying the protective effect of the GLP-1R agonist Ex-4 on hepatic steatosis in an in vitro cell model." (PMID 35140289, 2022). "GLP-1R agonist-induced weight loss reduces hepatic steatosis and increases insulin sensitivity in GLP-1R-expressing hepatocytes." (PMID 32079069, 2020). "Multivariate analysis revealed that the hepatic GLP-1R level was independently associated with hepatic steatosis." (PMID 30510243, 2018). "However, further investigations are warranted to decipher the complete mechanism underlying the protective effect of GLP1R agonists against hepatic steatosis." (PMID 35140289, 2022). "In addition, we found that the lower GLP-1R expression is associated with the severity of hepatic steatosis." (PMID 30510243, 2018). "Compared to the control diet, the ethanol diet resulted in a very significant increase in hepatic steatosis (perilipin 2 staining) and this was significantly less in the GLP-1R agonist-treated ethanol diet group." (PMID 40968135, 2025). "A systematic review including 6313 participants confirmed the efficacy of GLP-1R agonists on hepatic steatosis and inflammation." (PMID 40869400, 2025). "It was expected, and we confirmed that with free access to ethanol, GLP-1R agonists would reduce ethanol intake, liver steatosis, inflammation and ROS." (PMID 40968135, 2025). "First, this paper discusses drugs that were originally targeted for Type 2 DM such as glucagon-like peptide 1 receptor agonist, pioglitazone, and sodium-glucose transport 2 inhibitors, which are now being considered for treating fatty liver disease." (PMID 40943823, 2025). "In obese rats, reduced protein expression of both β-catenin and GLP-1R exacerbates hepatic steatosis induced by fatty acids in rat hepatocytes." (PMID 38727268, 2024). "Specifically, in an NAFLD mouse model, butyrate alleviated hepatic steatosis by enhancing hepatic glucagon-like peptide-1 (GLP-1) sensitivity via increased GLP-1 receptor (GLP-1R) expression." (PMID 39125336, 2024). "Synbiotics is the combination of probiotics and prebiotics in a formulation and, as such, has the advantage of producing increased levels of butyrate, which can upregulate GLP-1R expression to decrease hepatic steatosis." (PMID 39834471, 2024). "In conclusion, combined GIPR/GLP1R agonism additively attenuates hepatic steatosis and lowers hepatic inflammation, ameliorating liver injury during the development of NAFLD in E3L.CETP mice." (PMID 37379656, 2023). "We interpretate that GIPR and GLP1R agonism additively attenuate hepatic steatosis, lower hepatic inflammation, ameliorate liver injury, together preventing NAFLD development in humanized APOE∗3-Leiden.CETP mice." (PMID 37379656, 2023). "The current study in humanized E3L.CETP mice demonstrates that GIPR and GLP1R agonism additively attenuate hepatic steatosis, lower inflammation and ameliorate liver injury in the context of HFHC diet-induced NAFLD development." (PMID 37379656, 2023). "We demonstrate that GIPR and GLP1R agonism additively attenuate hepatic steatosis, lower inflammation, ameliorate liver injury, and together prevent the development of NAFLD." (PMID 37379656, 2023). "Here, we find that combining an inhibitor of liver ACLY, bempedoic acid, and the GLP-1R agonist liraglutide reduces liver steatosis, hepatocellular ballooning, and hepatic fibrosis in a mouse model of NASH." (PMID 37729871, 2023). "Sodium butyrate improved liver steatosis by upregulating GLP-1R expression and p-AMPK/p-ACC, by inhibiting HDAC2." (PMID 36077368, 2022). "The extent of clearance of hepatic steatosis with ALT-801 is particularly striking in comparison to the GLP-1R only agonist, semaglutide." (PMID 35461369, 2022).
Hepatic steatosis (continued). "Circulating GLP-1 reaches pancreatic β cells and binds to GLP-1R, thus promoting the release of insulin, reducing insulin resistance and improving hepatic steatosis." (PMID 36119048, 2022). "In the HFD-fed mouse model, hepatic GLP-1 levels were decreased, and sodium butyrate was reported to increase the expression of GLP-1R and decrease hepatic steatosis." (PMID 32717871, 2020). "GLP-1R agonists have been shown to reduce hyperlipidaemia, hypertension and fatty liver in diabetic patients." (PMID 32717871, 2020). "In conclusion, our study reveals that liraglutide attenuates hepatic steatosis via activation of autophagic flux, especially the GLP-1R-TFEB-mediated autophagy-lysosomal pathway." (PMID 33330497, 2020). "Many studies in mice show improvement and the possibility of preventing hepatic steatosis using different GLP-1R agonists." (PMID 33324348, 2020). "Glucagon receptor agonists combined with glucagon-like peptide 1 receptor agonists (dual agonists) improve dyslipidemia and reduce hepatic steatosis." (PMID 31068828, 2019). "A few studies in humans have also proven that utilization of GLP-1R agonists can improve hepatic steatosis, particularly in type 2 diabetes patients with NAFLD (as reviewed in 11)." (PMID 25230688, 2014). "Finally, perhaps someone with fatty liver disease would benefit more from a GLP‐1R/GCGR co‐agonist than an agent targeting GIPR, if equally efficacious for weight loss." (PMID 41287212, 2026). "SGLT2i and GLP1-R agonists are antidiabetic agents gaining an emerging role in managing MASLD, with an increasing body of evidence from both experimental and clinical studies in reducing hepatic steatosis and lowering associated cardiovascular risk." (PMID 40869400, 2025). "The review highlighted improvements with pioglitazone and lanifibranor (PPAR agonists), as well as with liraglutide and semaglutide (GLP-1R agonists), showing improvements in hepatic steatosis and lobular inflammation, and in some cases, resolution of NAFLD without exacerbating fibrosis." (PMID 40896767, 2025). "Here we used a well validated Bscl2-null (seipin knockout) mouse model of CGL type 2 (CGL2) to examine the effectiveness of a GLP-1R agonist, in treating lipoatrophic diabetes, hepatic steatosis and hyperphagia in CGL to inform the adoption of this class of drugs for individuals with lipodystrophy." (PMID 38745956, 2024). "Promisingly, new anti-diabetic drugs like sodium-glucose cotransporter 2 (SGLT2) inhibitors and glucagon-like peptide 1 receptor agonists (GLP-1RAs) are being investigated for their potential to reverse liver steatosis and halt the progression of severe fibrosis." (PMID 38323033, 2024). "As with other aspects of this study, we believe the work presented provides important new insights regarding exactly how fatty liver disease in lipodystrophy may respond to GLP-1R agonist treatment." (PMID 38745956, 2024). "Besides lowering food intake, we observed that GIPR and GLP1R agonism exerted a synergistic effect on increasing fecal energy and lipid excretion, which likely contributed to the attenuated hepatic steatosis through lowering lipid availability." (PMID 37379656, 2023). "The anti-inflammatory effects of GIPR and GLP1R agonism may be indirect and a consequence of attenuated hepatic steatosis, as lipid accumulation in itself is a potent inducer of inflammation." (PMID 37379656, 2023). "Recently, in phase 2 clinical trials, using glucagon-like peptide-1 receptor (GLP-1R) agonists (like liraglutide and semaglutide) in patients with NAFLD has also been shown to significantly improve inflammation, hepatic steatosis, fibrosis, and promote weight loss." (PMID 37893185, 2023). "Indeed, GLP-1 is closely related to hepatocyte fatty acid β-oxidation and insulin sensitivity, and GLP-1R in hepatocytes modulated insulin signaling, thereby ameliorating hepatic steatosis." (PMID 35655996, 2022).
Hepatic steatosis (continued). "Furthermore, liraglutide suppressed hepatic steatosis via the restoration of autophagy, in particular the GLP-1R- transcription factor EB (TFEB)-mediated autophagy-lysosomal pathway." (PMID 36230573, 2022). "We have performed a systematic review and meta-analysis of randomized controlled trials (RCTs) to evaluate the efficacy and safety of glucagon-like peptide-1 receptor agonists (GLP-1RAs) in the treatment of hepatic steatosis and fibrosis in patients with T2DM and NAFLD." (PMID 34956080, 2021). "Our findings also provide the first evidence of the inhibitory role of insulin on the basal expression of GLP-1R, which might explain why liraglutide could alleviate the insulin aggravated hepatic steatosis." (PMID 33746742, 2020). "Thus, our findings suggest that liraglutide attenuated hepatic steatosis via restoring autophagic flux, specifically the GLP-1R-TFEB-mediated autophagy-lysosomal pathway." (PMID 33330497, 2020). "Similarly, in the NAFLD mouse model, mice fed with a high-fat diet showed reduced hepatic GLP-1R expression, which was reversed by NaB treatment and accompanied by markedly alleviated liver steatosis." (PMID 30510243, 2018). "As early as 2008, researchers proposed that liver steatosis could be prevented by a DDP-4 inhibitor des-fluoro-sitagliptin (DFS) due to a reduction in ER stress in the liver by GLP-1R signaling." (PMID 29721506, 2018). "Interestingly, Exendin-4, i.e. a glucagon-like peptide-1 receptor agonist improved fatty liver disease in ob/ob mice by regulating glucose transporter expression; alike SREBP1c mediates glucose-stimulated GLUT2 gene expression in hepatocytes." (PMID 30547786, 2018). "The improvement of hepatic steatosis and presumably inflammation is likely due to activation of GLP-1R on hepatocytes, because others have shown that exenatide stimulates hepatocyte expression of PPARα and PPARγ that improve hepatic fatty acid oxidation, lipid export, and insulin sensitivity." (PMID 24188631, 2013). "A novel finding of this study was the observation that expression of GLP-1R is proportional to exendin-4 concentration and exendin-4 could attenuate fatty liver through activation of Sirt1." (PMID 22363635, 2012). "Higher MASLD regression in individuals with T2DM may be partly attributed to the use of glucose-lowering agents such as sodium-glucose cotransporter-2 inhibitors or glucagon-like peptide-1 receptor agonists, which can improve hepatic steatosis independently of lifestyle changes." (PMID 40665356, 2025). "Insulin might aggravate hepatic steatosis and liver injury by inhibiting GLP-1R expression." (PMID 33746742, 2020). "Thus, our findings demonstrate that GLP-1R, as a target of ExA, may prevent or ameliorate hepatic steatosis in obese and diabetic mice." (PMID 32079069, 2020). "Moreover, Sirt1 mediates the protection of a GLP-1R agonist on HFD-induced hepatic steatosis." (PMID 30533173, 2018). "In the current study GIPR and GLP1R agonism additively lowered food intake and body weight confirming previous reports in mice, which may at least in part explain the additive reduction of hepatic steatosis upon treatment with both agonists as it lowers the flux of nutrients towards the liver." (PMID 37379656, 2023). "GLP-1 receptor (GLP-1R) agonism was found to reduce body weight and hepatic steatosis, as well as increased hepatic fatty acid oxidation and insulin sensitivity in NAFLD/NASH." (PMID 36994336, 2021). "Liraglutide, a glucagon-like peptide-1 receptor (GLP-1R) agonist, attenuates hepatic steatosis via the GLP-1R-TFEB-mediated autophagy pathway." (PMID 34366846, 2021). "Meanwhile, PKA signaling directly downstream of GLP-1R is also activated, indicating a direct involvement of hepatic GLP-1R in GLP-1 mediated alleviation of fatty liver and liver injury." (PMID 33746742, 2020).
Hepatic steatosis (continued). "Semaglutide, a GLP-1R agonist, improves gut microbiota, lipid profiles, and glucose metabolism, significantly improving MASLD and supporting its potential as a treatment for hepatic steatosis." (PMID 40869400, 2025). "Glucagon-like peptide-1 receptor agonists (GLP-1 RAs) may improve cardiovascular health by reducing appetite and weight through central nervous system effects, decreasing hepatic steatosis, and lowering triglyceride and LDL-C levels." (PMID 41296390, 2025). "Interestingly the GLP-1 receptor (GLP1R) agonists liraglutide and semaglutide as well as the orlistat have shown beneficial effects on the two hits typical of NAFLD, the hepatic steatosis and the inflammatory process." (PMID 38895630, 2024). "In humans, the hepatic expression of GlP-1R has also been questioned, even though earlier studies have reported its presence in human hepatocytes, and suggested that GLP1R decreased hepatic steatosis by modulating the insulin signaling pathway or activating lipid oxidation." (PMID 39607493, 2024). "Finally, a novel triple GLP1R/GCGR/GIPR agonist, HM15211, induced significant reductions in liver steatosis, fibrosis, and inflammation in mice; a phase 2 clinical trial is ongoing (NCT04505436)." (PMID 35203484, 2022). "In this study, the hepatic steatosis induced by the HFD was improved by both live and heat-killed B. virosa; thus, Butyricimonas may modulate hepatic lipogenesis via GLP-1R activation." (PMID 35655996, 2022). "Again, no patients were treated with pioglitazone or glucagon-like peptide-1 receptor agonists, which have been shown to reduce hepatic steatosis and improve cardiac function." (PMID 26252899, 2015). "In addition to attenuating hepatic steatosis, combined GIPR/GLP1R agonism strongly lowered hepatic inflammation as evidenced by a decreased number of moKCs possibly as a result of lowered expression of hepatic chemokines involved in leukocyte trafficking to the liver." (PMID 37379656, 2023). "Glucagon-like peptide-1 receptor agonists are useful treatment options for MASLD; however, the efficacy of oral semaglutide in treating liver steatosis/fibrosis has not been fully elucidated." (PMID 39861190, 2025).
insulinomas (101 papers, 2012 to 2026). "Ga-68 DOTA-Exendin-4 and F-18 exendin-4 are glucagon-like peptide-1 receptor analogues that show high diagnostic accuracy for benign insulinomas, but their lower expression is seen in malignant insulinomas." (PMID 40563663, 2025). "The objective of this study is to analyse the immunohistochemical GLP-1R expression and its association with clinicopathological features and patient outcome in a national series of insulinomas." (PMID 37894845, 2023). "In this study we analysed the immunohistochemical GLP-1R expression of fifty-two insulinomas in association with clinicopathological variables." (PMID 37894845, 2023). "The aim of this study is to evaluate the glucagon-like peptide-1 receptor (GLP-1R) expression in insulinomas and to analyse its association with clinicopathological features and patient outcome." (PMID 37894845, 2023). "We hypothesize that GLP-1R imaging will become a preoperative diagnostic tool to be used for many patients scheduled for open or laparoscopic insulinoma resection." (PMID 26034506, 2015). "We established a clinical-grade IHC assay for GLP-1R expression and demonstrated its specificity for staining islets of Langerhans in normal human pancreas and an insulinoma." (PMID 41312422, 2025). "For example, GLP-1 and exendin-4 acutely desensitize GLP-1R-dependent cAMP production in rat insulinoma INS-1 cells." (PMID 40024571, 2025). "This test also yields the promise of differentiating between insulinoma and nesidioblastosis since the density of GLP-1R in nesidioblastosis is higher than in normal beta-cells but lower than in an insulinoma." (PMID 40395710, 2025). "The importance of accurately localizing insulinoma for the success of minimally invasive surgery has been highlighted, and GLP-1R-targeting imaging is considered a promising approach, especially when other diagnostic tests prove ineffective." (PMID 40405975, 2025). "GLP-1R PET/CT is less sensitive in malignant insulinoma, as they lack GLP-1 receptor overexpression." (PMID 41375058, 2025). "This is reinforced by the maintenance of high levels of GLP-1R in insulinomas, highlighting again the need for a systematic functional characterization of pNETs." (PMID 40649254, 2025). "Glucagon-like peptide-1 receptors (GLP-1R) are localized on pancreatic β-cells, overexpressed, and homogenously distributed on benign insulinomas." (PMID 39125476, 2024). "Benign insulinomas express high levels of the glucagon-like peptide 1 receptor (GLP-1R) in 92% of cases, which therefore presents an attractive alternative target for nuclear imaging of insulinomas." (PMID 39419553, 2024). "PET imaging data revealed elevated uptake of radiotracer in GLP-1R positive insulinomas compared with that in low GLP-1R expressed MDA-MB-435 tumors." (PMID 38646656, 2024). "Summary of evidence & Comments PET/CT with GLP-1R-targeting radiopharmaceuticals is the preferred imaging modality in insulinomas." (PMID 39256216, 2024). "Exendin-4 is a molecular tracer which targets glucagon-like peptide-1 receptor (GLP-1R), which has the highest expression on insulinoma beta islet cells and consequently has a very high sensitivity and specificity in localizing pancreatic insulinomas." (PMID 39497809, 2024). "The expression of GLP-1R is higher in nesidioblastosis than in normal pancreatic tissue, but lower than in insulinoma cases, which can be also a drawback of this imaging method." (PMID 39497809, 2024). "Both radiotracers ([18F]FBEM-[Cys40]-exendin-4 and [18F]FBEM-[Cys0]-exendin-4) exhibited high binding affinities for GLP-1R-positive insulinomas cells." (PMID 38646656, 2024). "It exhibited high binding affinity (IC50 1.07 ± 0.48 nM) toward GLP-1R positive insulinomas cells, comparable to that of EM3106B (IC50 1.25 ± 0.37 nM) alone." (PMID 38646656, 2024). "In agreement with human databases, the staining of GLP-1R in these human cell lines was undetectable compared to INS-1 insulinoma cell line, which showed clear staining." (PMID 39607493, 2024).